FAM90A16 (family with sequence similarity 90 member A16)
Synonyms: FAM90A16P; FAM90A17P
Tractability: No criterion of Open Targets' tractability assessment is met for any kind of drug.
Gene: Protein-coding gene on chromosome 8 (7,730,739 to 7,733,749, forward strand). Ensembl gene ENSG00000285620.
Subcellular location (Human Protein Atlas): Nucleoplasm; Nucleoli
Homologues: Orthologues: mouse Fam90a1b (28% identical), mouse Fam90a1a (27% identical), rat Fam90a1l1 (26% identical). Paralogues in human: FAM90A17 (100% identical), FAM90A8 (99% identical), FAM90A9 (99% identical), FAM90A18 (99% identical), FAM90A19 (99% identical), FAM90A15 (98% identical), FAM90A13 (98% identical), FAM90A14 (98% identical), FAM90A23 (98% identical), FAM90A3 (98% identical), FAM90A5 (98% identical), FAM90A10 (98% identical), and 9 more.